CD4 (CD4 molecule)
Diseases named in the same sentence as CD4 in open-access papers (continued):
Sharing a sentence is not in itself a finding about the gene and the disease.
infection (continued). "The difference between DR1 and B10 mice was most distinct after NC infection; DR1 and B10 mice were clearly different at the level of CD4 T cell cytokine secretion patterns and the profile of IgG isotype expression after NC infection, but not after PR8 infection." (PMID 22457834, 2012). "Finally, our data suggests that CD4+ and CD8+ cells make equal and transient contributions toward production of IFN-γ in the lung during the first two weeks of infection, but are not sustained." (PMID 22428026, 2012). "It is thought that the early depletion of the GALT, the largest reservoir of CD4+ T cells in the body, is a blow from which the host may not recover even after prolonged ART in the chronic phase of infection." (PMID 22479485, 2012). "T cells expressed negligible amounts of IL-10 or IFN-γ in the lung and bronchoalveolar lavage fluid (BAL) on day 4 post RSV infection (not depicted), but both CD4+ and CD8+ T cells from the lung or airways frequently expressed IFN-γ and IL-10 on day 8 post infection." (PMID 22393401, 2012). "The involvement of non-conventional and conventional CD4+ T cells in the early polyclonal B cell response to P. chabaudi malaria was then investigated by analysing spleen B cells according to cellularity and CD69 expression on days 0, 4 and 7 of infection." (PMID 21814579, 2011). "Although there was a transient change in the level of IgM+, CD4+CD8-CD25+, CD4+CD8+CD25+, and CD4-CD8+CD25+ lymphocyte subsets after PCV2 infection and LPC vaccination (data not shown), a profound pattern of statistical difference between groups 1 and 3 was clear after wild-type CSFV challenge." (PMID 22129109, 2011). "While the effect of memory cells on lung innate cytokines was antigen-dependent, the resulting ‘protective state’ induced in the tissue was independent of infection or PAMP recognition, suggesting memory CD4+ T cells in the lung were able to orchestrate the early innate response." (PMID 21647373, 2011). "This contrasts the results at later time points (12 to >156 weeks post infection) in asymptomatic SIV-infected macaques, showing no or even a negative correlation between MxA and A3G mRNA level in PBMC and peripheral lymph nodes or CD4+ T-cells (p = 0.132)." (PMID 21955401, 2011). "The proportions of both IFN-γ-producing virus-specific CD4+ and CD8+ T cells in the CNS of poly IC pre-treated mice were markedly decreased at both time points (results at day 14 post-infection not shown) compared to those of the control mice without poly IC-treatment." (PMID 22189096, 2011). "In contrast to IIIBx where the relative rate of infection is not affected by DC-SIGN, the relative rate of infection of IIIB was increased by cis expression of DC-SIGN such that it was similar to that of the CD4-independent strain." (PMID 22163292, 2011). "However, the percentages of CD1d-α-GalCer-restricted CD4+ cells expressing CD69 in both WT and I-Ab-/- mice were not affected by infection." (PMID 21814579, 2011). "In the acute phase of infection after viral replication reaches high levels HIV-1 (in the case of humans) and SIV (in the case of non-human primates) destroy the majority of CD4+ T cells in draining lymphoid tissue, particularly gut-associated lymphoid tissue (GALT)." (PMID 21284901, 2011). "Infection of DCs was not the sole pre-requisite for the generation of specific CTLs, since AT-2-inactivated HIV-C-DCs induced a CD8+ T cell proliferation, too, and these were also able to elicit antiviral activity against HIV-infected CD4+ T cell targets." (PMID 20442876, 2010). "Available epidemiological and vaccine trial data strongly implicate the skin in a block to protective immunity dependent on the presence of skinstage parasites and functional CD4+ and rapid CD8+ exogenous-antigen presentation in the skin, and independent of prior bloodstage infection." (PMID 20502667, 2010).
infection (continued). "Although trans infection of CD4(+) cells by HIV-1-bound dendritic cells has also been proposed based on in vitro experiments, direct in trans infection has not yet been demonstrated to occur in vivo, and dendritic cells are relatively rare when compared to other circulating blood cells." (PMID 20011536, 2009). "As determined by periodical monitoring, these animals were in a steady state phase of infection since they had stable or slightly fluctuating moderate levels of viremia, high FIV antibodies titers, and moderately reduced circulating CD4+ T-lymphocytes counts (data not shown)." (PMID 19284578, 2009). "Furthermore, the course of infection was virtually indistinguishable in RAG−/− mice reconstituted with CD4+CD25−, CD4+CD25+ or a 10∶1 ratio of CD4+CD25−/CD4+CD25+ T cells." (PMID 18401464, 2008). "However, it has not been ruled out if the infection enhancement effects mediated by DC-SIGN are in fact cis or trans effects, since it appears to be two phases of DC-mediated HIV transfer to CD4+ T cells involving both of these mechanisms." (PMID 18371209, 2008). "Importantly, infection with HIV-1 IND64V (but not HIV-1 EnvVSV) was as efficient in eliciting ATM phosphorylation as HIV-1LAI, both in CD4+CXCR4+ HeLa cells and in CEM cells (not shown)." (PMID 18560558, 2008). "Thus, the increment in CD25+ cells during infection is not accompanied by preferential Foxp3 induction and represents an expansion of both CD4+CD25+Foxp3+ and CD4+CD25+Foxp3– T cells." (PMID 17563918, 2007). "Nevertheless, we observed increased frequencies of CD4 Th17 cells in peripheral blood of CT-infected TRAC participants compared to uninfected participants, and a further increase in participants without recurring infection compared to those who were reinfected with CT within a year after enrollment." (PMID 40793782, 2025). "The limited early pulmonary CD4+ T cell response in C3HeB/FeJ mice was not due to an absence of live M. tuberculosis in lung-draining lymph nodes for T cell priming, since viable M. tuberculosis was detectable in both C57BL/6 and C3HeB/FeJ mice at 14 days after infection with HN878." (PMID 40986319, 2025). "CXCR3–CCR6+ CD4+ T cells (CCR6+) formed the largest proportion of AIM+CD4+ T cells in both children and adults; however, AIM+CCR6+ cells were reduced in children compared with adults during the acute phase of infection (spike-specific: P = 0.001; non-spike-specific: P < 0.0001)." (PMID 40906527, 2025). "Notably, systemic depletion of human CD4 + cells, but not CD3 + cells, significantly abrogates infection resolution in fLX and induces persistent infection, supporting the dominant role of peripheral CD4 + monocytes over T-cells in the resolution of acute SARS-CoV-2 infection." (PMID 40920821, 2025). "Furthermore, combining RPA-T4 treatment with non-infected CD4+ T cell coculture had a synergistic effect and resulted in sustained and high levels of HIV-1-infected macrophages, reaching similar infection rates when using the lab-adapted strain NL4-3 compared to the primary isolates CH077 and THRO." (PMID 40130873, 2025). "We also found a lower proportion of CD4 T cells (cluster X) in individuals with a focal HPV infection than in uninfected individuals, suggesting that this population may not play a major role in controlling the infection locally." (PMID 39836629, 2025). "Since the overall number of total CD4+ and CD8+ T cells was not changed in the vaginal tract of these mice, this could indicate a selective reduction in mature T cells that can readily fight HSV-2 upon infection." (PMID 39650661, 2024). "Nevertheless, CXCR6 was highly expressed in CD4+ TIA cells from memory mice but also in NKG2D+CD4+CD44+ T cells from control mice, which could be stimulated to produce IFN-γ in vitro, but were not recruited to the site of infection in vivo, hinting toward alternative recruitment mechanisms." (PMID 38838013, 2024).
infection (continued). "The authors were also able to demonstrate the limited role of CD4+ cells (whose depletion did not seem to change the natural history of acute infection) and, conversely, the importance of CD8+ cells (whose depletion prolonged the duration of the infection and delayed the viral clearance)." (PMID 37108816, 2023). "Although IFN-γ production is characteristic of cognate T cell activation, S. Typhimurium-specific CD4+ T cells are likely capable of IFN-γ-independent mechanisms because bacterial clearance is impaired when CD4+ T cells, but not IFN-γ, is depleted during late stages of primary infection." (PMID 37733817, 2023). "In fact, HIV-1 induced PS exposure is a consequence of the infection-induced apoptosis, as similar PS exposure accompanied with the decrease of CD62L expression occurred in camptothecin (CPT), a topoisomerase inhibitor, treated CD4 T cells in the absence of infection." (PMID 36780482, 2023). "However, our study showed a significantly decreased TNF-α production in CD4+, CD8+ T cells and CD14+ monocytes in TB, and HIV co-infected with TB had obviously decreased TNF-α production in CD4+, CD8+ T cells and CD14+ monocytes under a natural infection status without external antigen stimulation." (PMID 37483385, 2023). "During early infection, neutrophils predominate in the S. aureus SSTI immune response, giving way to other cell populations including antigen-presenting macrophages and dendritic cells, non-natural killer innate lymphoid cells, CD4+ Th17 cells, CD8+ T cells, and γδ T cells in later infection." (PMID 36978425, 2023). "In the chronic phase, Plasmodium‐specific CD4+ T cells in IL‐27‐neutralized mice consisted mainly of CD127+KLRG1− and CD127−KLRG1+ subpopulations that displayed distinct cytokine production, proliferative capacity, and are maintained in a manner independent of active infection." (PMID 37855243, 2023). "Park and colleagues showed cellular division of naïve CD4+ T cells in the NALT using an OVA-specific adoptive transfer model system and bacterial i.n. infection, though their observations were made three days following infection and do not strictly demonstrate in situ activation in the NALT." (PMID 36555214, 2022). "The effect of pre-infection IL-2, GROα, IFNα2, and SDF1-α on CD4 decline is likely to be independent of VL and HIV replication and instead may be reflective of pre-infection immune state that is favourable in the context of HIV disease progression once the person is infected." (PMID 35165387, 2022). "While the lower CD4 T cell response contributed to better protection, the reduced CD8 T cell response could have resulted in lack of viral control post infection as our previous data showed that CD8 Gag responses were imperative in reducing the viral burden post infection." (PMID 35935987, 2022). "Moreover, 60% to 90% of CD4+ or CD8+ EM T lymphocytes produced IL-10 and/or TGF-β1, with up to 40% of the cells producing TNF-α and IFN-γ, and no clear indication of immunological function after infection." (PMID 35720410, 2022). "Intracellular cytokine staining (flow cytometry) data showed that IFN-γ+ CD4+ T and IFN-γ+ CD8+ T cells from the lungs were induced at higher levels in the VSA-1-adjuvanted sCal-vaccinated C57BL/6 mice than those in non-adjuvanted sCal and no vaccine (VSA-1 mock and naïve infection) groups." (PMID 36146461, 2022). "A specific CD4+ T cell proliferation rate was higher in OBI carriers (3.0%) and CHB carriers (3.2%) than in donors with resolved HBV infection (2%) or non-infected individuals (1.6%) (OBI vs. resolver or non-infection, P < 0.01; CHB vs. resolver or non-infection, P < 0.001)." (PMID 35464946, 2022). "Interestingly, another study showed that the average affinity of CD4+ T cells responding to murine LCMV decreased over the transition from effector to memory-dominated responses, regardless of whether the infection was acute or chronic." (PMID 35911755, 2022).
infection (continued). "Indeed, specific CD4+ and CD8+ memory T cells were found in close contacts tested negative by RT-PCR and seronegative, suggesting the possible development of SARS-CoV-2 T-cell immune response even in the absence of successful and detectable infection." (PMID 35309363, 2022). "Although the rate of individuals with detectable SARS-CoV-2-specific CD4+ T cells were significantly lower in the cancer group than the health control at day 180, the fraction of SARS-CoV-2-specific CD4+ T cells were still higher than people who had no SARS-CoV-2 vaccination or infection history." (PMID 36434092, 2022). "However, in the presence of FRCs, which can capture HIV-1 through HA-mediated interactions between CD44 on their surface and virion-incorporated CD44, unlike CD4+ T cells, HIV-1 dissemination may be efficiently mediated though trans-infection in SLOs." (PMID 34696365, 2021). "Hyperactivated CD4+ CD25+ T cells express furin which leads to elevated by TCR signaling in severe COVID-19 infection and may assist SARS-CoV-2 viral entry into host cells for a negative feedback loop exacerbating infection." (PMID 35004764, 2021). "Interestingly, HA1-DCpep stimulation did not result in a more pronounced CD4+ or CD8+ T cell proliferative response in the MLNs, whereas the increase was significant in the spleen, suggesting a dominant T cell response in the spleen during AIV infection." (PMID 34925386, 2021). "We recently showed in CB-HSC-NOJ mice that non-apoptotic CD4+ T-cell death including caspace-1+ pyroptosis and phosphorylated mixed-lineage kinase domain-like protein (pMLKL)+ necroptosis was induced in the spleen at 3 days post-HIV-1 challenge when HIV-1 productive infection was less visible." (PMID 33924786, 2021). "In addition, except that there was no prominent change in the proportion of CD226+CD4+ T cells at the 12th week after infection, CD226 expression on splenic T cells was notably higher than that of the control group since the 3rd week after infection." (PMID 34421855, 2021). "Though the difference between TNF-α expression by CD4+ T cells was not significantly different between low dose and high dose infection groups at week 3, there was a consistent increase in the TNF-α expression from pre-infection to week 3 in the high dose group." (PMID 34484203, 2021). "Interestingly, for the second panel, CD4+ T cells dual-positive for co-receptor CCR5 and β7 were conducive to trans-infection as evidenced by elevated, though not statistically significant, p24 levels in culture, highlighting a role for β7 in facilitating viral attachment to these cells." (PMID 33816339, 2021). "At present, there is no baseline CD4 count information of the diagnosed PLHIV in Bhutan, and therefore difficult to understand whether the cases are diagnosed late or the current HIV testing intervention is picking up the recent new infections." (PMID 33945664, 2021). "This is significant as previous studies have shown that an ongoing strong CD4+ proliferative response, especially that directed against NS3, was an important correlate of viral control and clearance, whereas comparable responses are absent in chronically evolving infection." (PMID 33343515, 2020). "While the mRNA delivery of hACE2 followed by infection with 5x104 FFU of SARS-CoV-2 did not allow our group to study viral pathogenesis in Ifnar1-/- mice, the delivery of hACE2 mRNA to our murine model allowed for the induction of a strong CD4+ and CD8+ T cell response to SARS-CoV-2." (PMID 33326500, 2020). "Further, since CD4CCR5+ cells are also quantified in the broader CD4 cell group, if there is a decrease in the parent group and the number of CD4CCR5+ cells remains the same, this results in a greater proportion of CD4CCR5+ cells, and not a greater number or density of HIV targets for infection." (PMID 32533883, 2020).
infection (continued). "Mice vaccinated with BCG 30 days prior to infection also showed a 1 Log10 reduction in CFU in lungs at days 30 and 60 post-infection, representing a 90% reduction in mycobacterial burden in the absence of either conventional CD4+ or CD8+ T cell mediated immunity." (PMID 32625209, 2020). "Hence, TBL is characterized by diminished frequencies of cytotoxic marker expressing CD4+, CD8+ T cells, and NK cells at the site of infection, which might reflect the lack of protective immune responses at the site of Mycobacterium tuberculosis infection." (PMID 33101317, 2020). "Similarly, Treg-depletion prior to acute infection with the attenuated MHV strain A59 led to increased numbers of apoptotic neurons in the brain but did not affect the CNS recruitment of virus-specific CD8+ and CD4+ T cells." (PMID 32131483, 2020). "HeLa-CD4 cells transfected with HDAC1 siRNA (Hs_HDAC1_5) or a non-related control siRNA (GFP-22 siRNA) were infected with HIV-1 NL4–3 and replication was monitored for 8 days by quantification of the p24 viral protein in cell supernatants at day 1, 2, 3, 5 and 8 post-infection (pi)." (PMID 31744547, 2019). "Moreover, cervical myeloid dendritic cells (CD14+ CD11c+) have been shown to efficiently take up R5-HIV strain, more so than lymphocytes (CD4+/low) and macrophages (CD14+ CD11c−) but do not show signs of productive infection at a later time point, unlike the lymphocyte population." (PMID 31156637, 2019). "The kinetics of CD4+ T-cell expression showed that while KOS usually had a higher peak than D22 (ICP22 null) on day 14 PI when lesion development is maximum, cytokine levels in ICP22 null–infected corneal cells increased to levels that did not significantly differ from KOS infection on day 28 PI." (PMID 31387116, 2019). "However, we did control for baseline CD4 count which, although perhaps not ideal due to inter-patient variability in the rate of CD4 decline prior to ART, is frequently used as a surrogate marker for duration of infection." (PMID 31721805, 2019). "While the absolute number of CD4+ T cells was not significantly affected, the absolute number of CD8+ T cells was much lower in CD43 mutant than in WT mice, suggesting that CD43 signaling contributes to the CD8+ T cells expansion in greater extent than to the CD4+ T cells during infection." (PMID 31197200, 2019). "On day 5 post-infection, the vast majority of antigen-specific IFN-γ+ T cells in the ear were derived from the CD44+CD4+T-bet+CD62L− effector population that had not divided, while very few IFN-γ+CD44+CD4+T-bet+CD62L+ T cells were found, and those that were found had undergone proliferation." (PMID 29922288, 2018). "Although the expression of PD-1 and CXCR5 significantly increased amongst both NK1.1 positive and negative CD4+ T cells between days 5 and 8 p.i., NK1.1+CD4+ T cells more frequently expressed PD-1 and CXCR5 relative to NK1.1−CD4+ T cells throughout the first two weeks of infection." (PMID 30374346, 2018). "In sum, the improved viral production observed in CD4+ T-cells after treatment with supernatants derived from 25 ng/ml MIF-treated infected MDMs could not to be explained by differential cell viability, infection percentage, or cell activation (measured by surface markers)." (PMID 29997630, 2018). "In contrast to the induction of CD4+ T cells producing cytokines upon stimulation with M2e peptides, mucosal vaccination with M2e5x VLPs induced low levels of M2e-specific cytokine producing CD8+ T cells, similar to those as detected in naïve mice after infection (data not shown)." (PMID 29324805, 2018). "Notably, the robust systemic antibody response developed quickly after infection and in the absence of a detectable systemic EHV-1 specific Th cell response, as evidenced by the lack of EHV-1-specific CD4+ cells in re-stimulated PBMC during the first 2–3 weeks pi." (PMID 30440016, 2018).